PLIN5 (perilipin 5)
Description:
Lipid droplet-associated protein that maintains the balance between lipogenesis and lipolysis and also regulates fatty acid oxidation in oxidative tissues. Recruits mitochondria to the surface of lipid droplets and is involved in lipid droplet homeostasis by regulating both the storage of fatty acids in the form of triglycerides and the release of fatty acids for mitochondrial fatty acid oxidation. In lipid droplet triacylglycerol hydrolysis, plays a role as a scaffolding protein for three major key lipolytic players: ABHD5, PNPLA2 and LIPE. Reduces the triacylglycerol hydrolase activity of PNPLA2 by recruiting and sequestering PNPLA2 to lipid droplets. Phosphorylation by PKA enables lipolysis probably by promoting release of ABHD5 from the perilipin scaffold and by facilitating interaction of ABHD5 with PNPLA2. Also increases lipolysis through interaction with LIPE and upon PKA-mediated phosphorylation of LIPE (By similarity).
Synonyms: LSDP5; OXPAT; LSDA5; MLDP
Tractability: Small molecule: a high-quality ligand is known. PROTAC: a small molecule that binds it is known.
Gene: Protein-coding gene on chromosome 19 (4,522,531 to 4,535,247, reverse strand). Ensembl gene ENSG00000214456.
Subcellular location: Lipid droplet; Cytoplasm; Mitochondrion
Subcellular location (Human Protein Atlas): Lipid droplets; Vesicles
Gene Ontology:
Molecular function: protein binding; identical protein binding; lipase binding
Biological process: lipid droplet organization; lipid storage; negative regulation of fatty acid beta-oxidation; negative regulation of lipase activity; negative regulation of peroxisome proliferator activated receptor signaling pathway; negative regulation of reactive oxygen species metabolic process; negative regulation of triglyceride catabolic process; positive regulation of fatty acid beta-oxidation; positive regulation of lipase activity; positive regulation of lipid storage; positive regulation of triglyceride biosynthetic process; positive regulation of triglyceride storage; mitochondrion localization; negative regulation of lipid catabolic process
Cellular component: lipid droplet; cytoplasm; cytosol; mitochondrion
Genetic constraint (gnomAD): Loss-of-function variants: 31 observed, 27.42 expected, observed/expected ratio (o/e) 1.13, 90% interval 0.85 to 1.52. The upper end of that interval is the gene's LOEUF score, 1.52, which puts it in group 6 of 6, group 1 being the genes least tolerant of losing a copy. Missense variants: 666 observed, 565.32 expected, observed/expected ratio (o/e) 1.18, 90% interval 1.11 to 1.26. Synonymous variants: 297 observed, 249.33 expected, observed/expected ratio (o/e) 1.19, 90% interval 1.08 to 1.31.
Homologues: Orthologues: macaque PLIN5 (94% identical), dog PLIN5 (82% identical), pig PLIN5 (81% identical), guinea pig PLIN5 (79% identical), mouse Plin5 (71% identical), rat Plin5 (70% identical), chimpanzee PLIN5 (60% identical), tropical clawed frog plin3 (37% identical), zebrafish plin3 (27% identical), Drosophila melanogaster Lsd-2 (15% identical). Paralogues in human: PLIN3 (36% identical), PLIN2 (31% identical), PLIN4 (25% identical), PLIN1 (22% identical).
Diseases named in the same sentence as PLIN5 in open-access papers:
PLIN5 is named in the same sentence as 64 diseases in open-access papers, as found by Europe PMC text mining. Sharing a sentence is not in itself a finding about the gene and the disease. The quoted sentences say what the papers report.
Insulin resistance (19 papers, 2016 to 2026). Increased resistance towards insulin, that is, diminished effectiveness of insulin in reducing blood glucose levels. "Recently, it was reported that Plin5 deficiency can induce insulin resistance in the skeletal muscle and liver." (PMID 37667357, 2023). "Leptin-deficient mice exhibited myocardial hypertrophy, insulin resistance and altered substrate utilization, and Plin5 deficiency exacerbated myocardial hypertrophy in leptin-deficient mice." (PMID 37667357, 2023). "As an important target for improving insulin resistance/deficiency, Plin5 provides new ideas for future treatment of DC." (PMID 35509833, 2022). "In line with this, specific hepatic knockdown of Notch1 in mice resulted in an upregulated expression of glucose-6-phosphatase (G6P) and Plin5, leading to a predisposition of a diabetic phenotype through development of insulin resistance." (PMID 34067931, 2021). "In accordance with our results, hepatocytes from liver-specific PLIN5 KO mice display fewer LD-mitochondria contacts, reduced hepatic TG synthesis and FA oxidation, and are more susceptible to develop hepatic insulin resistance." (PMID 34869541, 2021). "It has been described that a global or muscle specific PLIN5 deficiency alleviated muscle insulin resistance in mice." (PMID 31384284, 2019). "Fasting produces an increase in insulin resistance and mitochondrial dysfunction associated with higher presence of PLIN5 in LDs." (PMID 28676863, 2017). "The ability to store excess fat in skeletal muscle in PLIN5+ LDs upon a prolonged fast associates with blunting of fasting-induced insulin resistance and mitochondrial dysfunction." (PMID 26864436, 2016). "This associates with blunting of fasting-induced insulin resistance and mitochondrial dysfunction, suggesting a role for PLIN5 in the modulation of fasting-mediated lipotoxicity." (PMID 26864436, 2016). "We further show a causal link between down-regulation of PLIN5 and insulin resistance in vivo in mouse skeletal muscle." (PMID 27922115, 2016). "To date, PLIN5 is the only member of the perilipin family that has been directly linked to LD turnover and fat oxidation in multiple models of insulin resistance." (PMID 26864436, 2016). "According to previous studies, Plin5 also can improve insulin resistance by mediating the JNK pathway." (PMID 35509833, 2022). "In this scenario, Plin5−/− mice present a phenotype characterized by insulin resistance due to impairment in glucose disposal in skeletal muscle and WAT, but not in the liver." (PMID 34067931, 2021). "In summary, hepatic PLIN5 traps the dietary excess of fatty acids in lipid droplets, protecting hepatic from insulin resistance and damage induced by high-fat diet feeding." (PMID 33276146, 2021). "For instance, research in Plin5−/− mice showed an improvement of glucose tolerance in liver and insulin resistance in muscle." (PMID 34067931, 2021). "PLIN5 plays an important role in triacylglycerol metabolism and insulin action in skeletal muscle, and PLIN5-null mice developed skeletal muscle insulin resistance." (PMID 29409445, 2018). "The two perilipin genes PLIN4 and PLIN5 are known to be involved in lipid droplet coating and lipid metabolism, with PLIN5 playing a role in insulin resistance." (PMID 29409445, 2018). "To examine the effect of PLIN5 on lipid-induced insulin resistance we overexpressed PLIN5 in rat skeletal muscle and observed a profound increase in intramyocellular LD content while insulin-stimulated glucose uptake was not impaired." (PMID 26864436, 2016). "Collectively, while PLIN5 knockdown promotes insulin resistance in skeletal muscle of chow-fed mice, it paradoxically partly protects skeletal muscle against HFD-induced insulin resistance." (PMID 27922115, 2016). "The current work demonstrates for the first time that PLIN5 protects against palmitate-induced insulin resistance and facilitates FA oxidation in response to muscle contraction and increased metabolic demand in vitro." (PMID 27922115, 2016).
Insulin resistance (continued). "Of note, PLIN5 overexpressing myotubes were partly protected from palmitate-mediated insulin resistance and lipotoxicity." (PMID 27922115, 2016). "In the present model of physiological insulin resistance, PLIN5+ LDs were more numerous and larger than PLIN5− LDs." (PMID 26864436, 2016). "This highlights for the first time that down-regulation of PLIN5 promotes insulin resistance in a muscle-autonomous fashion." (PMID 27922115, 2016). "Jointly, our observation that expansion of PLIN5+ LDs ameliorates mitochondrial lipotoxicity and lipid-induced insulin resistance is in line with rodent data indicating a protective role for PLIN5 in lipid-induced insulin resistance and hepatic lipotoxicity." (PMID 26864436, 2016). "Perilipin 5 (PLIN5) is a LD protein whose mechanistic and causal link with lipotoxicity and insulin resistance has raised controversies." (PMID 27922115, 2016). "Jointly, these data indicate that the fasting-mediated increase of PLIN5 on the LD surface is part of the adaptive response to fasting to alleviate lipid-induced insulin resistance and to maintain mitochondrial function." (PMID 26864436, 2016). "Remarkably, hepatic steatosis induced by PLIN5 did not cause hyperglycemia or hepatic inflammation and even protected from high-fat diet-induced insulin resistance." (PMID 33276146, 2021). "Therefore, extrapolation of the present findings to women must be done with care, especially given the sex differences previously reported for myocellular lipid handling, lipid-induced insulin resistance, response to fasting and PLIN5 content." (PMID 26864436, 2016). "Additionally, IMAT could directly modulate insulin resistance (IR), independently of other body fat depots, by secreting inflammatory cytokines and expressing the perilipin 5 (Plin5) gene." (PMID 37899436, 2023). "For instance, Plin5 expression could promote lipolysis in IMAT in patients with insulin resistance." (PMID 37899436, 2023). "In recent years, studies have shown that Plin5 expression is involved in the pathogenesis of DC lipid toxicity, such as oxidative stress, mitochondrial dysfunction, endoplasmic reticulum (ER) stress, and insulin resistance (IR) and has become a key target of DC research." (PMID 35509833, 2022). "Therefore, we next asked whether altering PLIN5 expression in islets would influence systemic insulin resistance detected by ITT as a few AAV were also detected in insulin targeted tissues such as liver, muscle and visceral fat." (PMID 31384284, 2019). "We hypothesised a role for PLIN5 in modulating fasting-mediated insulin resistance." (PMID 26864436, 2016). "Thus, expanding the pool of LDs decorated with PLIN5 could be considered an adaptive response to fasting to maintain LD dynamics and prevent insulin resistance." (PMID 26864436, 2016). "On the other hand, Plin5 can reduce the activity of the JNK pathway and reduce the inhibition of IRS-1, thus achieving the effect of improving insulin resistance." (PMID 35509833, 2022). "It is hence remarkable that South Asians developed insulin resistance upon a HFHC-diet, despite having higher levels of PLIN5 protein than Caucasians." (PMID 28195217, 2017). "In Caucasians, the LD coat protein PLIN5, which is involved in regulating oxidative lipolysis, seems to be protective against HFHC diet-induced insulin resistance." (PMID 28195217, 2017). "Therefore, we hypothesised a role for PLIN5 in modulating fasting-induced insulin resistance." (PMID 26864436, 2016).
steatosis (19 papers, 2016 to 2026). Increased lipid within the cytoplasm of cells. "Under a high-fat diet, loss of PLIN5 in hepatocytes protected from steatosis but resulted in hepatic damage and inflammation." (PMID 34571805, 2021). "A very recent study localized the expression of PLIN5 in numerous healthy and diseased human tissues, including liver obtained from subjects with steatosis, acute liver injury as well as mitochondrial deficiency syndrome." (PMID 30893876, 2019). "Wild-type (WT) PLIN5 overexpression in WD-fed mice reduced steatosis and improved redox state despite continued WD consumption." (PMID 39803529, 2024). "From the over-represented KEGG pathways we selected those with known role in stopping or slowing progression from steatosis to hepatocarcinogenesis and all of the genes are more increased in Plin5-/–WD animals than in WT-WD." (PMID 39469452, 2024). "As we and others have previously reported, Plin5 deficiency can alter the progression of MAFLD by reducing inflammasome formation, hepatic injury, and steatosis." (PMID 39469452, 2024). "ATGL-deficient mice at 12–13 weeks of age demonstrated microvesicular steatosis of the liver shortly before cardiac death, with increased expression of perilipin 2 and slight downregulation of perilipin 5, as measured by immunohistochemistry." (PMID 36611868, 2022). "Plin5 enhances the expression of lipids, accelerates lipolysis, and promotes lipid utilization during lipid increase and steatosis." (PMID 35509833, 2022). "Plin5 can promote FA synthesis and storage of TG in LD to reduce lipid toxicity in physiological states of steatosis and its related oxidative stress, inflammation, IR, ER stress, and other pathological processes." (PMID 35509833, 2022). "PLIN5 promotes lipid storage, and it is also increased in human steatosis." (PMID 35740312, 2022). "A steatosis-like model of primary mouse and human hepatocytes, showed that statins decrease the levels of PLIN5, but not other LD-associated genes via the sterol regulatory element-binding protein 2 (SREBP2)." (PMID 34067931, 2021). "Similarly, expression of Plin5, which also promotes hepatic fat storage, is lower in PPARα−/− mice, despite these mice showing more pronounced steatosis." (PMID 30866796, 2019). "Therefore, the inhibition of lipophagy along with the continuous production of small LDs engulfed by PLIN2, PLIN3, and PLIN5 could be a proposed mechanism for NAFLD progression from simple steatosis to NASH." (PMID 37958873, 2023). "Interestingly, in the livers of hepatocyte-specific perilipin 2 knockout mice treated with an HFD and CDAA diet, leading to steatosis and steatohepatitis, upregulation of perilipin 5 was observed concomitant to a decrease in inflammation, cell death and fibrosis (parallel manuscript in preparation)." (PMID 36611868, 2022). "Plin5−/− livers had an increased expression of CAV1 under NC and HFD in comparison with WT, supporting our results for reduced steatosis and liver damage in those mice." (PMID 32481590, 2020). "Our data highlight a protective role of Plin5 against hepatic lipotoxic injuries induced by HCV NS5A, which is helpful for understanding the steatosis and injuries in liver during HCV infection." (PMID 30954078, 2019). "Recently, we showed that hepatic PLIN5 expression is regulated by LCN2, controlling intracellular lipid droplet formation in experimentally-induced steatosis." (PMID 30893876, 2019). "Simultaneously, our data indicated the protective role of Plin5 against hepatic lipotoxic injuries induced by HCV NS5A, which is helpful to understand steatosis and injuries of the liver with HCV infection." (PMID 30954078, 2019). "Such limitations are especially relevant when analyzing Plin2 function in the liver, given that Plin5 binds and regulates the activity of ATGL, steatosis is exacerbated in Pnpla2 (ATGL)−/− mice, and as shown in this study, Plin5 is overexpressed in Plin2−/− livers." (PMID 37844775, 2023).
steatosis (continued). "The reduced activity of CMA failed to degrade Plin5 and other perilipin proteins (which are substrates of CMA), inhibited LD breakdown, and caused steatosis in hepatocytes." (PMID 35401929, 2022). "On the contrary, mice overexpressing liver-specific PLIN5 fed with a high-fat diet exhibit severe steatosis without worsening glucose homeostasis." (PMID 34869541, 2021). "Further, we show that PLIN5 function in BAT influences systemic glucose metabolism via secondary effects on iWAT (adipocyte size, thermogenic gene expression, inflammatory gene expression, insulin signaling, and lipolysis) and liver (steatosis, insulin signaling)." (PMID 34083525, 2021).
Hepatic steatosis (17 papers, 2012 to 2026). Steatosis is a term used to denote lipid accumulation within hepatocytes. "In contrast, specific deficiency of either Plin2 or Plin5 reduces LD accumulation, ameliorates hepatic steatosis, and delays the progression of MASLD." (PMID 41373932, 2025). "Therefore, Plin5 is likely to be critically involved in the development of pathologies associated with fatty liver." (PMID 35401929, 2022). "Studies have demonstrated that both Plin2 and Plin5 are significantly upregulated in mice with HFD-induced hepatic steatosis and in patients with fatty liver." (PMID 41373932, 2025). "Perilipin 5 was also found to be increased in the livers of fatty liver dystrophic mice and perilipin 5 knock-out mice were protected from hepatic steatosis." (PMID 36012215, 2022). "Perilipin 5 expression is elevated with hepatic steatosis and its ablation decreases lipid accumulation in the liver." (PMID 30477200, 2018). "Additionally, BAT PLIN5 overexpression led to healthy remodeling of inguinal white adipose tissue with improved systemic glucose tolerance and reduced diet-induced hepatic steatosis." (PMID 41509390, 2026). "In the MAFLD-HCC model, the loss of Plin5 in WD-fed mice preserved the level of OTU diversity compared to WD-fed WT animals, indicating that Plin5 acts as a protective factor in preserving microbial diversity during fatty liver disease." (PMID 39469452, 2024). "All those indicate that Plin5 may contribute to the formation of liver steatosis possibly through inhibition of the release of FFAs from LDs." (PMID 35401929, 2022). "However, deleting PLIN5 in hepatocytes resulted in PPARa activation, which elevated mitochondrial FAO and prevented hepatic steatosis at the expense of causing hepatic damage and inflammation." (PMID 33276146, 2021). "We further show that promoting PLIN5 function in BAT is associated with healthy remodeling of subcutaneous white adipose tissue and improvements in systemic glucose tolerance and diet-induced hepatic steatosis." (PMID 34083525, 2021). "Therefore, ameliorating ERS to enhance PPARγ and promote lipolysis of LD mediated by Plin2 and Plin5 may be an effective way to prevent hepatic steatosis." (PMID 41373932, 2025). "To evaluate the potential effects of Plin5 in NASH progression, we examined Plin5 KO mice in an HFHC diet-induced NASH model with induced hepatic steatosis, inflammation and fibrosis, features similar to human NASH." (PMID 37349836, 2023). "PLIN5 ameliorates NAFLD, alleviates hepatic steatosis and fibrosis, and protects against hepatic injury in NAFLD." (PMID 37108378, 2023). "Our studies reported here suggest the potential of PLIN5 to mimic the effect of cold temperature on BAT and, thereby, to improve systemic glucose tolerance and protect against diet-induced hepatic steatosis." (PMID 34083525, 2021). "To determine whether Plin5 participates in the development of NASH, we identified Plin5 expression changes in two murine models of fatty liver disease." (PMID 37349836, 2023). "In addition, we show that the effects of PLIN5 in BAT secondarily lead to smaller adipocytes in iWAT, to improved systemic glucose tolerance and insulin sensitivity, and to protection from hepatic steatosis on a high-fat diet (HFD)." (PMID 34083525, 2021).